RFPL4B (ret finger protein like 4B)
Synonyms: RNF211
Tractability: No criterion of Open Targets' tractability assessment is met for any kind of drug.
Gene: Protein-coding gene on chromosome 6 (112,347,330 to 112,351,294, forward strand). Ensembl gene ENSG00000251258.
Gene Ontology:
Molecular function: ubiquitin protein ligase activity
Biological process: innate immune response; regulation of gene expression
Cellular component: cytoplasm
Genetic constraint (gnomAD): Missense variants: 314 observed, 343.65 expected, observed/expected ratio (o/e) 0.91, 90% interval 0.83 to 1. Synonymous variants: 118 observed, 133.66 expected, observed/expected ratio (o/e) 0.88, 90% interval 0.76 to 1.03.
Homologues: Orthologues: pig RFPL4B (57% identical), dog RFPL4B (56% identical), mouse Rfpl4b (33% identical), rat AABR07045341.1 (33% identical). Paralogues in human: RFPL1 (36% identical), RFPL3 (35% identical), RFPL2 (35% identical), RFPL4A (33% identical), RFPL4AL1 (32% identical), RNF135 (22% identical), SPRYD4 (11% identical), CD80 (6% identical), RNF152 (6% identical), CD86 (5% identical), CD274 (5% identical), PDCD1LG2 (5% identical).
Diseases named in the same sentence as RFPL4B in open-access papers:
RFPL4B is named in the same sentence as 5 diseases in open-access papers, as found by Europe PMC text mining. Sharing a sentence is not in itself a finding about the gene and the disease. The quoted sentences say what the papers report.
liver cancer (1 paper, 2024). An epithelial or non-epithelial malignant neoplasm that arises from the liver. "Next, we analyzed the expression levels of RFPL4B in different liver cancer cell lines through the CCLE database and found that RFPL4B was expressed at the highest level in the Huh7 cell line." (PMID 39323867, 2024).
cancer (1 paper, 2024). A tumor composed of atypical neoplastic, often pleomorphic cells that invade other tissues. "Since RFPL4B has rarely been studied in cancer, we intend to further explore its biological function in HCC." (PMID 39323867, 2024).
tumor (1 paper, 2024). "In our study, we confirmed by in vitro experiments that the knockdown of RFPL4B could repress tumor progression of Huh7 cells." (PMID 39323867, 2024).
RFPL4B also shares sentences with these, for which no sentence is quoted: fragile X syndrome (1 paper); schizophrenia (1).